MMP13 (matrix metallopeptidase 13)
Diseases named in the same sentence as MMP13 in open-access papers (continued):
Sharing a sentence is not in itself a finding about the gene and the disease.
breast carcinoma (continued). "In similar fashion, breast cancer cells induce MMP-13 production from osteoblasts, and the subsequent MMP-13 action on a variety of substrates promotes metastasis to the bone." (PMID 24549119, 2014). "On the other hand, Pit-1 overexpression and MMP-13 knockdown completely blocked breast cancer invasiveness to lung." (PMID 25527274, 2014). "A selective MMP-13 inhibitor was found to delay breast cancer growth and cancer-induced bone osteolysis." (PMID 24549119, 2014). "MMP13 is upregulated in metastatic breast cancer patient samples and is part of a gene signature that is a predictor of prognosis in breast cancer lymph node metastasis." (PMID 24811120, 2014). "Stromal MMP-13 expression is known to be required for the invasion and metastases of breast cancer and melanoma." (PMID 24581230, 2014). "In this study we evaluate the relationship between Pit-1 and two collagenases: matrix metalloproteinase-1 (MMP-1) and matrix metalloproteinase-13 (MMP-13), which have been related to metastasis in breast cancer." (PMID 25527274, 2014). "Our data indicated that knockdown of MMP-13 blocked mammary cancer invasiveness to lung in xenografts with Pit-1 overexpression." (PMID 25527274, 2014). "Collagen I is a particularly strong SHG emitter in vivo, is a substrate for MMP13, is increased in breast cancer stroma, and is an important contributor to TACS." (PMID 24010522, 2013). "Collagenase-3/MMP-13 is the most recently identified member of the collagenase subfamily, originally isolated from breast carcinoma." (PMID 24369907, 2013). "In this work we have directly shifted a mouse model of breast cancer from one TACS state to another by knockout of stromal MMP13, implicating stromal MMP13 as one driver of TACS state." (PMID 24010522, 2013). "MMP-13 (collagenase-3) was originally isolated from human breast cancer tissue, and has been shown to be an important contributor to breast (and other) cancer pathology." (PMID 24010522, 2013). "This analysis clearly indicated that Collagen I in mammary tumor peripheries of WT mice was more highly oriented (i.e. more ordered; C closer to 1), than in the mammary tumor peripheries of MMP13 KO mice (less ordered, C closer to 0)." (PMID 24010522, 2013). "Together these results suggest that depletion of host (stromal) MMP13 – a key collagen degrading enzyme – increased total collagen I content, but reduced collagen I organization, in the periphery of E0771 mammary tumors grown in MMP13 KO versus WT mice." (PMID 24010522, 2013). "We have shown that treatment with the MMP13-selective inhibitor Cmpd-1 reduced the growth rate of two different primary breast cancer models: The MDA-MB-231 human breast cancer xenograft and the 4T1.2 syngeneic mouse model." (PMID 22253746, 2012). "Collectively, our data suggest that MMP13-selective inhibitor Cmpd-1 significantly reduces breast cancer burden at both the primary tumor site and also in bone as a secondary site, where the severity of tumor-induced bone osteolysis was also reduced." (PMID 22253746, 2012). "MMP13 (collagenase-3) originally identified in human breast cancer tissue is viewed as a potential tumor marker for breast cancer diagnosis and its expression is correlated with metastasis formation." (PMID 22822400, 2012). "Recently, a role of MMP-13 in promotion of bone metastasis and breast cancer invasiveness has been reported." (PMID 22723936, 2012). "Here, we demonstrated the functional involvement of MMP-13 in breast cancer bone metastasis: MMP-13 activated pre-MMP-9 and cleaved galectin-3 on OC precursors." (PMID 22032644, 2011). "MMP-13 was originally identified from a cDNA library derived from a breast carcinoma and subsequently found to be produced by tumours of different sources." (PMID 22032644, 2011). "MDA-MB-231 breast cancer cells that express MMP-13 were used as a model for in vitro and in vivo experiments." (PMID 22032644, 2011).
breast carcinoma (continued). "MMP-13 was up-regulated in breast cancer cells after in vitro stimulation with IL-8 and was responsible for increased bone resorption and osteoclastogenesis, both of which were reduced by MMP inhibitors." (PMID 22032644, 2011). "A correlation between the high expression of MMP-13 in breast cancer tissue and a higher rate of distant metastases, poor prognosis and in addition a higher expression of MMP-13 in early stage tumors was shown." (PMID 19531263, 2009). "In accordance to this, we also identified higher amounts of MMP-13 mRNA and pro-form in breast cancer tissue." (PMID 19531263, 2009). "We conclude that the expression pattern of Mmp13 mRNA in myofibroblasts of invasive carcinomas in the MMTV-PyMT breast cancer model recapitulates the expression pattern observed in human breast cancer." (PMID 18698413, 2008). "In the current study, we examined a cohort of 263 Chinese breast cancer specimens and report the evidence that MMP-13 correlated with more aggressive breast cancer." (PMID 18373849, 2008). "MMP-13 plays an important role in tumor progression in numerous human malignancies, including colorectal cancer, breast cancer, squamous cell carcinomas, and melanoma." (PMID 18554405, 2008). "Matrix metalloproteinase (MMP) 13 (collagenase 3) is an extracellular matrix remodeling enzyme that is induced in myofibroblasts during the earliest invasive stages of human breast carcinoma, suggesting that it is involved in tumor progression." (PMID 18698413, 2008). "Human collagenase-3 (MMP-13) is a recently identified member of the matrix metalloproteinase (MMP) family that was originally isolated from breast carcinoma." (PMID 18554405, 2008). "Using combined in situ hybridization and immunohistochemical staining, we verified that most of the Mmp13 mRNA positive cells were positive for the myofibroblast marker α-smooth muscle-actin, paralleling the expression we found in human breast cancers." (PMID 18698413, 2008). "Our study suggests a potential application of MMP-13 as an independent biomarker for breast cancer prognosis." (PMID 18373849, 2008). "The goal of current study was to evaluate the prognostic values of MMP-13 expression level and its tissue distribution pattern in a large cohort of human breast cancer patients." (PMID 18373849, 2008). "Human collagenase-3 (MMP-13) is a member of matrix metalloproteinase family of enzymes that was originally identified in breast carcinomas and subsequently detected during fetal ossification and in arthritic processes." (PMID 18554405, 2008). "This IHC study of TMA with 263 specimens of Chinese breast cancer provided the first evidence that MMP-13 is highly expressed by both the tumor cells and adjacent fibroblast cells." (PMID 18373849, 2008). "Since this expression pattern is similar to what we have observed in human breast cancers, we chose the MMTV-PyMT mouse breast tumor model to test the functional role of MMP13 in breast cancer progression and metastasis." (PMID 18698413, 2008). "To determine the role of MMP13 in mouse mammary tumor progression, we took a genetic approach using Mmp13−/− mice." (PMID 18698413, 2008). "The activation of MMP-13 in human breast cancer cells was prevented by plasminogen activator inhibitor-1 but not by tissue inhibitor of metalloproteinase-1, suggesting that plasmin activates MMP-13 directly." (PMID 15701164, 2005). "Elevated MMP-13 expression has been documented in numerous malignancies [e.g., breast carcinoma, colorectal cancer, vulvar SCC, skin SCC, HNSC, BCC (in focal areas of keratinized cells)] and associated with tumor behavior and patient prognosis." (PMID 15291964, 2004). "Subtype 3 had the upregulation of MMP13, a well-studied tumor marker in breast cancer cells." (PMID 40004168, 2025). "Therefore, the existing pathways that activate or inhibit MMP13 expression in breast cancer are also discussed, with the hope of providing more ideas for the prognosis of breast cancer." (PMID 40243781, 2025).
breast carcinoma (continued). "Additionally, the silencing of the lncRNA PART1 reduced the expression of MMP13, thereby inhibiting the development of breast cancer." (PMID 40243781, 2025). "Therefore, the expression of MMP13 in relation to these properties can be exploited for breast cancer therapy." (PMID 40243781, 2025). "Furthermore, collagen reorganisation can be driven by MMP13 to create a more suitable environment for breast cancer cell development." (PMID 40243781, 2025). "Furthermore, HA inhibited EMT and osteoblast activators in breast cancer cells, including MMP‐9 and MMP‐13, which regulate breast cancer‐induced osteolysis." (PMID 39947253, 2025). "The pro-oncogenic transcription factor STAT3 forms a positive feedback loop with some of the inflammatory cytokines, including IL-6, and promotes MMP13 expression in murine breast cancer CAFs; furthermore, MMP13 plays an important role in maintaining the function of CAFs." (PMID 40243781, 2025). "In addition to CAFs and TAMs, MMP13 promotes other cells in the TME to regulate the malignancy of breast cancer." (PMID 40243781, 2025). "Among the MMPs, MMP13 is considered to be a key factor affecting the prognosis of breast cancer." (PMID 40243781, 2025). "LINC00511 binds to the MMP13 protein to promote breast cancer cell migration and proliferation." (PMID 38233788, 2024). "The identification of IL-11, as well as of MMP-1 and MMP-13, which are also mediators of breast cancer metastasis to the bone, supports the hypothesis that PKD2 and PKD3 contribute, via the secretome, to the colonization of the bone in TNBC." (PMID 38323010, 2024). "GOLM1 could promote breast cancer cell aggressiveness by regulating matrix metalloproteinase-13 (MMP13)." (PMID 39190284, 2024). "MMP-13 may be vital for the invasion and metastasis of breast cancer cells and may be helpful as a prognostic marker when assessed simultaneously with lymph node status and HER2 expression." (PMID 38291367, 2024). "LINC00511 may upregulate the expression of MMP13 by acting as a miR-150 sponge, thereby promoting breast cancer cell proliferation, migration, and invasion." (PMID 38408075, 2024). "Several studies suggest that ATF2 may function as an oncogene, worsening the outcome of the disease, as it increases the transcription of genes such as MMP2, MMP13, cyclin A, and aromatase that contribute to the progression and metastasis of breast cancer." (PMID 37955015, 2023). "The increased transcription of MMP13 by AFT2 may play a role in facilitating the metastasis of breast cancer to bone." (PMID 37955015, 2023). "Importantly, we also observed that the accumulation of CRP2 in the nucleus of breast cancer cells is associated with an increase in the expression of MMP-9 and MMP-13 transcripts." (PMID 37266453, 2023). "In agreement, miR-203 and miR-135 reduced the expression of MMP-13 in breast cancer cells, which could partially account for the reduced bone metastases in mouse models in these studies." (PMID 35158995, 2022). "A higher MMP-13 level occurs at the tumour–bone interface of breast cancer." (PMID 35805035, 2022). "Physical interaction networks however detected only COL3A1, suggesting it could be a gene of interest that CTHRC1, POSTN and MMP13 could use to regulate the tumour matrisome in breast cancers." (PMID 36190948, 2022). "In breast cancer, increased MMP13 is related to bone metastasis." (PMID 35413833, 2022). "Inflammatory cells or osteoblasts could also produce PTHrP to stimulate MMP-13 secretion to promote breast cancer bone metastasis." (PMID 35805035, 2022). "MMP-13 expression was found to be upregulated in bones of a metastatic TNBC mouse model or at the tumor-bone interface from syngeneic mice injected with mammary tumor cell lines with metastatic potential." (PMID 36741729, 2022). "MMP13 played an important role in the metastasis and invasion of cancer and may be used as one of the prognostic indicators of breast cancer, particularly in Her2 subtype." (PMID 35069702, 2021).
breast carcinoma (continued). "However, our study demonstrated that sauchinone inhibits MMP13 expression by inhibiting the phosphorylation of CREB in breast cancer cells." (PMID 34643237, 2021). "In addition, circRNACER mediates breast cancer malignant progression by targeting the miR136/MMP-13 axis." (PMID 33958507, 2021). "Therefore, MMP13 is an important molecular target in breast cancer progression, highlighting the need to identify and develop clinically effective therapeutic agents." (PMID 34643237, 2021). "Among MMPs, MMP13 is well known for its effects on breast cancer progression." (PMID 34643237, 2021). "In addition, the targeted inhibition of MMP13 by sauchinone represents a promising approach for the treatment of breast cancer." (PMID 34643237, 2021). "In addition, we performed an MMP13 rescue experiment with the Mmp13-knockdown breast cancer cells to ensure that MMP13 is a potential target for the inhibitory effect of sauchinone on breast cancer cell migration." (PMID 34643237, 2021). "This study showed that MMP-13 was a moderator for tumor invasion and metastasis and could be an independent predictor of poor prognosis in breast cancer." (PMID 34452576, 2021). "Overexpression of MMP13 at the tumor-bone interface triggered mammary tumor-induced osteolysis." (PMID 34643237, 2021). "In breast cancer resulting from bone metastasis, MMP-13 deregulation may alter osteoblast morphology and bone resorption through differentiation of pre-osteoclasts, osteoclast activation, and osteolysis." (PMID 32116759, 2020). "MMP13, derived from stroma in the immediate vicinity of tumor cells, was identified along the invasion and metastasis of breast cancer, renal cell carcinoma, squamous cell carcinoma, and melanoma, supporting a crucial role of the microenvironment for tumor growth." (PMID 32042099, 2020). "A recent investigation revealed that the upregulation of MMP-13 in the tumor-stromal interaction, especially at the tumor-bone interface, is crucial to tumor-induced osteolysis, suggesting the potential value of MMP-13 in the treatment of breast cancers with bone metastasis." (PMID 32793401, 2020). "A positive correlation between GREM1 and MMP13 expression was observed in breast cancer patients." (PMID 33287358, 2020). "We, for the first time, showed that GREM1 could regulate multiple MMPs, especially MMP13, in breast cancer cells." (PMID 33287358, 2020). "Notably, we found a relationship between GREM1 and MMP13 expression in breast cancer metastasis for the first time." (PMID 33287358, 2020). "ATF2 has been found to increase the transcription of matrix metalloproteinase 13 (MMP13), which may help facilitate breast cancer bone metastasis." (PMID 33198803, 2020). "Finally, we showed that ETV4 and MMP13 co-overexpression is correlated with poor prognosis in breast cancer." (PMID 29996935, 2018). "Indeed, to decipher the relevance of ETV4 and MMP13 association in breast cancer, we assessed MMP13 and ETV4 mRNA expression levels in a series of 456 breast cancer samples." (PMID 29996935, 2018). "Finally, we investigate the ETV4-MMP13 link in breast cancer samples and describe that the association of both ETV4 and MMP13 overexpression is associated with poor patient outcome." (PMID 29996935, 2018). "MMP13 potentiates the effects of the ETV4 oncogene during breast cancer genesis and progression." (PMID 29996935, 2018). "High MMP13 and ETV4 mRNA expression levels were associated with negative ER status (P = 0.00067) and the HR−/ERBB2+ subtype (P = 0.0015), two parameters associated with breast cancer aggressiveness." (PMID 29996935, 2018). "MMP‐13 (collagenase 3) expression was first discovered in breast cancer." (PMID 29744196, 2017). "Moreover, the expression of MMP‐13 has an important role in the pathogenesis of osteolysis by tumor cells in bone metastasis of human breast cancer 34 and prostate cancer." (PMID 26817521, 2016).
breast carcinoma (continued). "Remarkably, several studies from Pérez-Fernández's group have demonstrated that 1,25(OH)2D3 represses the expression of the gene encoding the pituitary transcription factor 1 (PIT1) in breast cancer cells and that PIT1 silencing downregulates SNAIL1, MMP1, and MMP13 proteins." (PMID 26880977, 2016). "Further we conclude that the main contributors to extracellular proteolysis of murine breast cancer TICs are metalloproteases, such as Mmp14, Mmp2, and Mmp13 along with aspartic proteases, because treatment with TAPI-O and Pepstatin strongly reduced DQ-collagen cleavage." (PMID 27542270, 2016). "Stromal MMP13 mediates tumor microenvironment and promotes lung metastasis of breast cancer." (PMID 27356745, 2016). "For example, the expression of MMP9, MMP13 and MMP14 all correlated with poor survival in patients with breast cancer, and expression of MMP1 and MMP2 was associated with highly aggressive breast cancer that metastasizes rapidly to the lung." (PMID 26956475, 2016). "Induction of MMP13 production by breast cancer cells has also been shown to facilitate metastasis." (PMID 25664615, 2015). "Our observation can generate a hypothesis that ERBB2 and S100A7A-mediated MMP13 expression can contribute to the subtype-specific spatial growth patterns in breast cancer." (PMID 26669540, 2015). "MMP13 expression has been observed in invasive malignant tumors such as breast carcinomas, squamous cell carcinomas (SCCs) of the head and neck and vulva, primary and metastatic melanomas, hepatocellular carcinoma cell lines and transitional cell carcinoma of the urinary bladder." (PMID 25880591, 2015). "We showed that alteration of RKIP expression affected MMP13 transcripts in breast cancer cells." (PMID 26308852, 2015). "MMP13 plays a role in invasion of breast cancer cells through degradation of extracellular matrix." (PMID 26308852, 2015). "We found that the RKIP/MMP13 ratio predicts relapse-free survival in breast cancer patients." (PMID 26308852, 2015). "Furthermore, a recent study showed that silencing MMP13 in the stromal cells increased the rate of mammary cancer metastasis via mechanisms involving peri-tumoral collagen I remodeling." (PMID 26669540, 2015). "Thus, for example, it has been described that MMP-13 is produced by fibroblast-like cells located in the stromal compartment of the breast cancer tissue, whereas other studies have indicated that MMP-13 is synthesized predominantly by epithelial tumor cells." (PMID 25527274, 2014). "Human collagenase-3 (MMP-13) was first identified in breast carcinoma." (PMID 25527274, 2014). "This experimental finding could be in line with previous clinical data indicating that MMP-1 and MMP-13 seem to be related with different metastatic profiles in breast cancer." (PMID 25527274, 2014). "In mice, knockdown of MMP-13 blocks Pit-1-induced breast cancer cell invasiveness induced by Pit-1." (PMID 25527274, 2014). "Several studies suggested that MMP-13 might play a critical role in bone metabolism and even induce bone metastasis of breast cancer by activating MMP-9 and other enzymes." (PMID 25510449, 2014). "Therefore we investigated how MMP13 modulates collagen I, a principal collagen subtype in breast tissue, and affects tumor pathology and metastasis in a mouse model of breast cancer." (PMID 24010522, 2013). "Variations in expression of biomarkers in fibroblasts between different histological types was reported, demonstrating that invasive ductal breast carcinomas have high global expressions of MMPs, including MMP13, and TIMPs compared with the remaining types of breast carcinoma." (PMID 24229053, 2013). "Our data here suggest further that collagen I may be a principal contributor to these MMP13-regulated changes in collagen architecture and organization, at least in some mammary tumor models." (PMID 24010522, 2013).